HLA-E (major histocompatibility complex, class I, E)
Diseases named in the same sentence as HLA-E in open-access papers (continued):
Sharing a sentence is not in itself a finding about the gene and the disease.
tumor (continued). "HLA-E expression in tumor cells can be induced by IFN-γ stimulation." (PMID 39451228, 2024). "Furthermore, immunohistochemical experiments conducted on transplanted tumor models in nude mice confirmed significantly elevated levels of HLA‐E expression in tumor tissues from the IRF5 M1‐exos group compared to the M1‐exos group." (PMID 39623605, 2024). "The HLA-E molecule is attracting a gradually growing interest in tumor immunology." (PMID 39766165, 2024). "HLA-E expression levels are increased in tumor cells as compared to healthy tissues, resulting in the inhibition of cytotoxic NK cells and a subset of CD8 T lymphocytes via its interaction with heterodimer NKG2A/CD94, expressed specifically in those cytotoxic immune populations." (PMID 39766165, 2024). "In this regard, it is important to note that residual NKG2A expression might still hinder CAR-NK cell activity in vivo, due to potential upregulation of HLA-E on tumor cells following contact with IFN-γ secreted by NK cells." (PMID 39349459, 2024). "Tumors can deploy different mechanisms to escape from NK cells and differential expression of HLA-E and HLA-F may act synergistically to promote tumor survival." (PMID 38281021, 2024). "Additionally, recognition of the NKG2A axis, interacting with HLA-E on tumor cells, highlights its significance in immune evasion and cancer progression." (PMID 38473398, 2024). "Tumor cells such as HLA-E and immune cells such as CD8 and NK cells can express immune checkpoint molecules upon exposure to immune factors such as cytokines, which prevent NK and CD8 cell activation, even resulting in NK and CD8 cell dysfunction or exhaustion." (PMID 39229258, 2024). "HLA‐E (human leukocyte antigen‐E) is considered a promising target for tumor immunotherapy." (PMID 39623605, 2024). "In particular, colorectal, breast, and clear cell renal cancers exhibit a negative prognostic association with HLA-E expression, which appears to facilitate tumor immune evasion." (PMID 39584993, 2024). "Collectively, the data presented here demonstrate that BRY805 can activate natural killer (NK) cells, thereby enhancing NK cell-mediated cytotoxicity against HLA-E+ tumor cells, synergizing with PD-L1 inhibitors, cetuximab or trastuzumab, and inhibiting tumor growth in vivo." (PMID 39584993, 2024). "However, NK cell-mediated tumor killing is often impaired by the interaction between human leukocyte antigen (HLA)-E and the inhibitory receptor, NKG2A." (PMID 39349459, 2024). "This indicates that the combination of NK cells with approved small molecules which modulate HLA-E levels on tumour cells may have synergistic anti-tumour effects." (PMID 38223411, 2024). "In the field of oncology, a recent study explored the potential of rhesus cytomegalovirus (RhCMV) vectors, genetically engineered to trigger an HLA-E-restricted CD8+ T cell response targeting tumor-associated antigens (TAAs), in generating an effective anti-tumor reaction against prostate cancer." (PMID 39301027, 2024). "In addition to facilitating immune evasion, HLA‐E also exerts regulatory control over tumor growth through alternative mechanisms." (PMID 39623605, 2024). "The diselenide bond in this compound broke under low-dose γ-ray irradiation to produce selenite acid, which not only inhibited the expression of HLA-E on breast cancer cells, but also blocked the NK-expressed inhibitory immune checkpoint to promote tumor eradication through NK cells." (PMID 39065636, 2024). "By binding to receptors on NK cells or T cells, HLA‐E may facilitate the evasion of detection and clearance by the immune system for tumor cells." (PMID 39623605, 2024). "NK cells were the predominant immune cell interacting with circulating tumour cells in blood biopsies of metastatic pancreatic ductal adenocarcinoma patients, and in a transcriptomic analysis, the HLA-E:NKG2A axis was the most enriched interaction between these cells." (PMID 39200132, 2024).
tumor (continued). "Additionally, it inhibits the NKG2A ligand, HLA-E, which is overexpressed in the human tumor microenvironment (TME) and contributes to the reduction in lymphocyte expression within the TME." (PMID 39584993, 2024). "Furthermore, the expression of immune checkpoint molecule CD94/NKG2A in the CD8 and NK cells and/or their ligand HLA-E in the tumor cells is also regulated by immune factors such as cytokines." (PMID 39229258, 2024). "Indeed, HLA-E expression is upregulated concurrently with the downregulation of classic HLA I allotypes and the presence of free β2M in the cytoplasm of tumor cells." (PMID 38067396, 2023). "Of note, also downregulation of HLA-E, a molecule implicated in the regulation NK activity under certain conditions, did not affect tumor cell lysis in our systems." (PMID 37684704, 2023). "Studies have shown that HLA-E has a role in both tumor escape and tumor immune surveillance." (PMID 36829496, 2023). "HLA-E expression on tumor cells reduced NK cell cytotoxicity." (PMID 37675109, 2023). "In contrast to membrane HLA-E expression, the fluid component of HLA-E was shown to be differentially detectable in male and female tumor patients, allowing us to conclude sex differences in the immunological response against tumor tissue." (PMID 38069020, 2023). "Importantly, the expression of HLA-E greatly increases in several human malignancies with consequent inhibition of the effector functions of tumor-infiltrating lymphocytes (TILs) through its binding with NKG2A." (PMID 36831606, 2023). "It is now a well-known fact that HLA-E expression has clinical relevance, and it has a high impact on tumor progression, metastasis, and the reduced survival of patients with some tumors, e.g., in laryngeal, mammary, non-small-cell lung, ovarian, and colorectal carcinomas." (PMID 36829496, 2023). "One of the mechanisms causing the unsatisfactory anti-tumor ability of NK cells is that tissues in the TME express non-classical HLA class-I molecule HLA-E, which binds to the NK inhibitory receptor, CD94/NKG2A, and inhibits NK cells." (PMID 37144558, 2023). "However, as human leukocyte antigen E (HLA-E) can inhibit the activity of NK cells, the overexpressed of HLA-E within tumor protects tumor cells of various origins from lysis by natural NK cells." (PMID 37899463, 2023). "On the other hand, the overexpression of HLA-E in pathological conditions such as solid and hematological malignancies may be responsible for tumor escape from Vδ2 T cell-mediated immunosurveillance." (PMID 36831606, 2023). "In the tumor cohort, 22 (68.8%) patients had positive HLA-E values in the blood serum tested." (PMID 38069020, 2023). "Additionally, CRISPR/Cas9-induced NKG2A knockout in Vδ2 T cells activated and expanded in vitro enhances the killing of tumor cells, despite their HLA-E expression." (PMID 36831606, 2023). "The presence of NK cells could therefore induce HLA-E upregulation, and in turn, enable tumor resistance towards NK cell cytotoxicity." (PMID 38067178, 2023). "However, the number of studies addressing sex differences in soluble HLA-E concentration in tumor patients is sparse." (PMID 38069020, 2023). "Indeed, the CD94/NKG2A complex expressed on Vδ2 T cells is able to efficiently block the killing of tumor cells expressing HLA-E molecules." (PMID 36831606, 2023). "Thus, a standard Cr51‐release killing assay on parental (HLA‐Elow) and transfected (HLA‐Ehigh) CAL‐27 tumor cells confirmed that monalizumab enhanced NK‐cell killing, to a larger extent in the case of HLA‐E‐expressing tumors." (PMID 37782273, 2023). "Notably, the expression of genes encoding MHC class I molecules, such as human leukocyte antigen (HLA)-A, HLA-B, HLA-C, and HLA-E, and beta-2 microglobulin, significantly decreased in After Tumor." (PMID 38136558, 2023).
tumor (continued). "Moreover, IFN-γ was found to be responsible for promoting the expression of histocompatibility leukocyte antigen chain E (HLA-E) in tumour cells, which inhibits the anti-tumour responses of CD8+ T cells and NK cells." (PMID 37503572, 2023). "Not only tumor cells use the upregulation of HLA-E as a mechanism to escape the immune response." (PMID 38069020, 2023). "Therefore, the interaction between surface HLA-E on tumor cells and NK receptors usually leads to tumor escape from NK lysis." (PMID 38007483, 2023). "Whether HLA-E and HLA-F expression promotes immune evasion from NK and T cells or contribute to expand the HLA repertoire on tumor cells remains to be established." (PMID 38318504, 2023). "Especially in colorectal and breast carcinomas, a negative prognostic association of HLA-E expression seems to facilitate tumor escape." (PMID 36829496, 2023). "A recent study proved that selenic acid could block HLA-E expression and facilitate cellular apoptosis in tumor cells, which evokes NK cells-mediated antitumor activity." (PMID 37899463, 2023). "HLA-E is typically expressed on normal healthy cells to protect them from NK cell-mediated killing and this system can be manipulated in cancer to the advantage of the tumour." (PMID 36839682, 2023). "Future studies will be necessary to determine if the overexpression of HLA-E by tumor cells is secondary to IFN-γ secretion in these highly infiltrated tumors or secondary to DNA damage that may lead to type I IFN production." (PMID 35267497, 2022). "Since HLA-E is expressed virtually on all human tissues and allows for self-recognition, increased expression of HLA-E in several tumors constitute a mechanism of tumor escape that evades immune effector responses." (PMID 36429001, 2022). "HLA-E (membrane staining) was expressed in tumor cells more heterogeneously." (PMID 36077799, 2022). "Furthermore, HLA-E on tumor cells was identified as an independent positive prognostic biomarker in HGSOC." (PMID 35267497, 2022). "The propensity for HLA‐E expression in malignant cells is still not fully understood, and it has been suggested that tumours may upregulate HLA‐E and HLA‐G to escape killing by immune cells." (PMID 35596615, 2022). "High HLA-E expression on tumor cells was associated with a longer OS (median OS not reached vs. 52.9 months, p = 0.002)." (PMID 35267497, 2022). "Monalizumab is an anti-NKG2A blocking mAb that not only boosts NKG2A+NK cell responses against HLA-E+ tumor cells but also promotes the effectiveness of durvalumab (a mAb that blocks PD-L1) by increasing the functional activity of NKG2A+PD-1+ NK cells against HLA-E+PD-L1+ target cells." (PMID 36291830, 2022). "Since Face-2 is recognized as an important component of cancer cells, these polyreactive mAbs can never be diagnostic tool for tumor-associated HLA-E." (PMID 35214796, 2022). "Its ligand, HLA-E is expressed by many different tumor cells." (PMID 35757002, 2022). "Having established that numerous tumor types upregulate HLA‐E/Qa‐1b levels as a mechanism to resist the killing of NK and T cells, NKG2A checkpoint inhibitors have been developed and demonstrated to unleash their cytotoxic activity against tumors in both preclinical and clinical investigations." (PMID 37693065, 2022). "Our results indicate that peptides displayed by HLA‐E molecules on tumour cells might influence the effectivity of NKG2A‐ICI therapy and potentially suggest novel approaches for patient stratification, for example, based on tumoral HLA‐G levels." (PMID 35596615, 2022). "Utilising an anti-HLA-E mAb with CD16 binding properties may allow for activation of an ADCC response by NK cells against HLA-E expressing tumour cells, in addition to NKG2A signalling blockade." (PMID 36560403, 2022).
tumor (continued). "HLA-E overexpression may be caused by the interaction of tumor cells with tumor microenvironment (TME), and there was evidence that IFN-γ produced by tumor-reactive immunocytes contributed to the upregulation of HLA-E within tumor cells." (PMID 36032104, 2022). "We observed high level of HLA-E in primary tumor cells obtained from 4 patients with HNSCC." (PMID 36341402, 2022). "We also analyzed whether HLA-E expression in tumor cells displayed any correlation with immune cell density." (PMID 34952595, 2021). "However, the presence of anti-tumor immune cells led to the upregulation of inhibitory molecules, namely HLA-E, in cancer cells, suggesting that the latter can evade the tumor-suppressing immune response through NKG2A/HLA-E binding." (PMID 34199324, 2021). "Comparable to HLA-G, HLA-E can be expressed on tumor cells, stroma cells or both." (PMID 34201079, 2021). "We then assessed whether selinexor modulated the expression of HLA-E on primary tumor cells using samples derived from patients with CLL." (PMID 34926302, 2021). "However, HLA-E/β2m, preferentially overexpressed in metastases compared with primary tumors and associated with CD94+ tumor infiltrating lymphocytes (TILs), was associated with a poor overall survival." (PMID 34211852, 2021). "However, the absence or downregulation of HLA class Ia can promote the expression of new tumor peptides presented by HLA-E, therefore activating unconventional CD8+ T cells through HLA-E–peptide–specific recognition by TCRs." (PMID 33652996, 2021). "The inhibitory potential of HLA-E has been established in multiple tumor models." (PMID 34203549, 2021). "This was in part due to the low expression of FAS on the tumor cells compared to HLA-E." (PMID 33968044, 2021). "Indeed, we have previously shown that overexpression of HLA-E/β2m by tumor cells (primary tumors) characterizes a subgroup of 23% of CRC." (PMID 34211852, 2021). "Furthermore, in vitro data based on CRC cell lines showed that aberrant cell surface expression of HLA-E/β2m by tumor cells inhibits the cetuximab-mediated cellular cytotoxicity by NK cells." (PMID 34211852, 2021). "A recent study identified that HLA-E suppresses NK cell sensitivity to tumor cells and that resistance to immune checkpoint blockade therapy in multiple clinical studies correlates with an NK sensitivity gene signature, including HLA-E." (PMID 34926302, 2021). "Interestingly, our study showed strong association of five HLA genes (including HLA-DMA, HLA-DMB, HLA-DOA, HLA-DRB6 and HLA-E) with delayed tumor recurrence in both cohorts." (PMID 34834481, 2021). "The median number of tumor cells with HLA-E expression per mm2 was 1085.3 (range 10.7 – 4602.1)." (PMID 34952595, 2021). "Indeed, IFN-γ secreted by immune cells during anti-tumor immune responses upregulates the expression of HLA-E on tumor cells." (PMID 33255582, 2020). "It is reasonable that a higher HLA-E expression on tumor cells will destroy NK cell function." (PMID 32411806, 2020). "NKG2A dimerizes with CD94 to bind HLA-E molecules loaded with tumor peptides." (PMID 33391277, 2020). "Notably, the PEBL-transduced NKG2Anull NK cells displayed a more effective antitumor capacity against HLA-E+ tumor cells in vivo than blockade with anti-NKG2A mAb." (PMID 32714324, 2020). "The inhibitory receptors NKG2A and the killer-cell immunoglobulin-like receptors (KIRs), through the binding with their respective ligands HLA-E and HLA-A on tumor cells, suppress cytokine secretion and hamper direct cytotoxicity of NK cells against target cells." (PMID 33312177, 2020). "As HLA-E overexpression is negatively correlated with survival and exhibited in the majority of tumor types, blocking this NKG2A/HLA-E inhibition could enhance immunotherapy across an array of tumors, including OC." (PMID 31456796, 2019).
tumor (continued). "In addition, HLA-E, the NKG2A ligand, is expressed in many highly aggressive tumors (e.g., lung, head and neck, colon, pancreas, and liver), and most cells in the tumor are HLA-E+." (PMID 32010130, 2019). "Furthermore, tumor biopsies can be monitored before and during the course of therapy using these monospecific HLA-E mAbs." (PMID 31009335, 2019). "HLA-E is proven to be a mediator for immune escape in virally infected cells and tumor cells." (PMID 30761272, 2019). "However, anti-tumor immunity and IFN-γ, in particular, promote HLA-E expression at the tumor cell surface." (PMID 31623687, 2019). "On the contrary, increased levels of IFN-γ in the tumor microenvironment may lead to up-regulation of HLA class I, and especially HLA-E, on the tumor cells leading to immune escape by inhibition of NK cells via the CD94/NKG2A receptor." (PMID 31681270, 2019). "Failure of cancer patients to respond to natural killer (NK) cell therapies could be due to HLA-E overexpression in tumor tissues." (PMID 31009335, 2019). "Interestingly, tumor cells reacted to immune infiltration by upregulating HLA-E, ligand of the inhibitory receptor NKG2A expressed by CD8 and NK cells." (PMID 30871626, 2019). "Interestingly, HLA-E expression is negatively correlated with the frequency of NKG2A+ CD8+ T cells in the tumor, suggesting that the accumulation of NKG2A+ CD8+ T cells in the tumor microenvironment is regulated by HLA-E." (PMID 32010126, 2019). "Our results also suggest that the accumulation of NKG2A+ CD8+ T cells in the tumor may be negatively regulated by HLA-E." (PMID 32010126, 2019). "Failure of patients to respond to NK therapy could be due to the level of expression of HLA-E on the tumor cell surface." (PMID 31009335, 2019). "Furthermore, we demonstrated in an earlier study that HLA-E levels on MM tumor cells are increased upon in vivo growth in the BM of immunodeficient mice as compared to in vitro passaged cells." (PMID 29988376, 2018). "A study revealed an increased expression of HLA-E associated with the absence of NK cells at tumor milieu and other study reported the downregulation of HLA-E by HPV E7 induced-methylation in human keratinocytes." (PMID 29976244, 2018). "Moreover, a recent paper has shown that under hypoxia and glucose deprivation, HLA-E can be upregulated in both human and mouse tumor cells as a result of microenvironmental stress." (PMID 29988376, 2018). "Interestingly, low glucose levels and hypoxic conditions have been shown to induce upregulation of the NKG2A ligand HLA-E on tumor cell lines but also in primary tissues." (PMID 30619362, 2018). "The interaction between the NKG2A receptor and its ligand, HLA-E, can have an inhibitory effect on the NK cell anti-tumor capacity and could outweigh the beneficial effect of improved licensing." (PMID 29988376, 2018). "Human leukocyte antigen (HLA)-E is highly expressed in a variety of tumors and, in addition to immune escape, may promote tumor growth via other mechanisms." (PMID 27322426, 2016). "In the univariate analysis, a low expression of non-classical HLA-E by tumor cells was associated with a strong reduced risk of death in this cohort (HR 0.632, 95% CI 0.406-0.984, p=0.042)." (PMID 26658106, 2016). "Here we studied their prognostic effect in the context of the expression of HLA molecules that are key in tumor recognition (HLA-A, B and C) or suppression of immunity (HLA-E) as this is still unknown." (PMID 26658106, 2016). "In a cohort of laryngeal carcinoma patients, HLA-E may be a biomarker of tumor invasiveness, but the definitive mechanism is unknown." (PMID 27322426, 2016). "This difference might be explained by the fact that we analyzed an advanced-stage, metastatic patient group, while HLA-E expression might be an earlier event in tumor progression." (PMID 27895918, 2016).